ASCL1 (achaete-scute family bHLH transcription factor 1)
Diseases named in the same sentence as ASCL1 in open-access papers (continued):
Sharing a sentence is not in itself a finding about the gene and the disease.
lung carcinoma (25 papers, 2009 to 2024). "ASCL1 is known to induce miR-375 transcription in lung cancer and its expression is associated with elevated neuroendocrine characteristics in lung cancer." (PMID 37869089, 2023). "For instance, high levels of RET expression in ASCL1+ tumours were associated with significantly shorter OS in stage 1 lung cancer and other lung adenocarcinomas." (PMID 27092013, 2016). "Because ASCL1 is necessary for the survival and proliferation of ASCL1High NE-lung cancer, targeting ASCL1 is a promising strategy to kill ASCL1High SCLC." (PMID 31324758, 2019). "We further show, both at RNA and protein levels, that the secreted protein IGFBP5 correlates with NE-lung cancer cells expressing ASCL1." (PMID 31324758, 2019). "Consistently with this, in lamin B1–depleted cells we observed binding of the Ret promoter by the transcription factor Ascl1, which has been shown to directly activate Ret expression and play an important role in lung cancer development." (PMID 31015297, 2019). "The transcription factor Ascl1 directly activates Ret expression and plays an important role in lung cancer development." (PMID 31015297, 2019). "We know that ASCL1 is important in pulmonary neuroendocrine cell development, lung injury repair, airway dysplasia, and neuroendocrine differentiated lung cancer pathogenesis." (PMID 25705890, 2015). "In lung cancer cells ASCL1 negatively regulates the expression of Dickkopf homologue 1 (DKK1), an antagonist of the Wnt/β-catenin signalling pathway which is involved in the development of the exocrine pancreas and in pancreatic beta cell proliferation." (PMID 19744316, 2009). "Moreover, individual CSCs in SCC (CD44+CD34+ITGA6+), lung cancer (ASCL1+/CGRP+ neuroendocrine cell) and breast cancer (CD44+CD24-, GSE124887) show concurrent activation of stemness genes, nuclear factors and mitochondrial components." (PMID 37463926, 2023). "Recent studies have discovered molecular subtypes of SCNE lung cancer defined by ASCL1 (achaete-scute family bHLH transcription factor 1), NEUROD1 (neurogenic differentiation 1), POU2F3 (POU class 2 homeobox 3), and YAP1 (Yes1 associated transcriptional regulator) transcription factors." (PMID 37467967, 2023). "Additionally, some ASCL1 targets were ranked among the top twenty regulators including SOX2 whose overexpression has been clearly described in lung cancers." (PMID 33778495, 2021). "The transcriptome of NE-lung cancers driven by ASCL1 or NEUROD1 has been well studied." (PMID 31324758, 2019). "Therefore, we propose that a similar mechanism to that in lung carcinoma cells promotes the degradation of Ascl1 when quiescent hippocampal stem cells express high levels of Id4." (PMID 31552825, 2019). "Loss- and gain-of-function experiments in human bronchial epithelial and lung carcinoma cell lines revealed that Ascl1, MMP-7 and MGMT are able to protect cells from the tobacco-specific nitrosamine NNK-induced DNA damage and the alkylating agent cisplatin-induced apoptosis." (PMID 23300791, 2012). "For example, Achaete-Scute homologue-1 (ASCL1), a pro-neural transcription factor, is important in pulmonary neuroendocrine cell development, injury repair, and highly expressed in neuroendocrine differentiated lung cancer functioning as a regulator of RET oncogene." (PMID 25705890, 2015). "This was also supported by ASCL1 (Mash1 human homolog), which regulates INSM1 gene through E2-box binding in NE lung cancer cells." (PMID 37627018, 2023). "Promoters of ASCL1-and NEUROD1-dependent genes were found as specific targets of lurbinectedin in SCNE lung cancer cells." (PMID 37467967, 2023). "In both lung cancers, lung adenocarcinoma (LUAD) and lung squamous cell carcinoma (LUSC), ASCL1 ranked among the top five putative regulators." (PMID 33778495, 2021). "First, we validated two of the most significantly altered genes, ASCL1 and AMOTL2, in a subset of 20 subjects (13 lung cancer patients and 7 controls)." (PMID 25705890, 2015).
lung carcinoma (continued). "Of these 64 mRNAs, 38 mRNAs were down-regulated in lung cancer patients, of which the top 5 mRNAs were CHGB, B4GALT1, ZNF434, GLB1, and ASCL1 (p≤0.0001)." (PMID 25705890, 2015). "ASCL1 was highly expressed in classic small cell lung cancer (SCLC); additionally, it was a key driver of tumorigenesis in classic SCLC and correlated with the survival and development of lung cancers with neuroendocrine (NE) features." (PMID 36755810, 2023). "Thus, ASCL1 is likely to negatively regulate DKK1 transcription in these tumours, as has been shown to occur in A549 lung cancer cells." (PMID 19744316, 2009). "Thus, ASXL3-high SCLC cells might have a similar feature as ASCL1-high SCLC cells, such as being essential for neuroendocrine (NE) lung cancer development." (PMID 32669118, 2020). "ASCL1 has been found to repress DKK1 transcription, a negative regulator of the Wnt signalling pathway in lung cancer cells, and is also the first transcriptional repressor identified for DKK1." (PMID 19744316, 2009). "Thus, ASCL1 and NEUROD1 expression has been used to divide NE-lung cancers into ASCL1High, NEUROD1High, or double-negative subtypes." (PMID 31324758, 2019).
neuroendocrine tumors (19 papers, 2010 to 2025). "We further annotated tumor cells using four markers closely associated with neuroendocrine tumors: ASCL1, NCAM1, INSM1, and GRP." (PMID 40213972, 2025). "ASCL1 encodes for a transcription factor acting as a master regulator of neurogenesis, is overexpressed in neuroendocrine tumors and a promising therapeutic target in small cell lung cancer (SCLC)." (PMID 29344090, 2018). "NEO2734 and BET inhibitors suppress neuroendocrine tumor growth by downregulating ASCL1 expression, thereby inhibiting cell cycle progression." (PMID 40165961, 2025). "Both tumors were negative for the epithelial marker p63 (marker for squamous cell carcinoma) and the neuroendocrine markers calcitonin gene related protein (CGRP) and Achaete-scute complex homolog-1 (MASH1/ASCL1), characteristic of neuroendocrine tumors." (PMID 35954335, 2022). "Among these, the bHLH family TF ASCL1, a well-known neuronal differentiation regulator, is required by neuroendocrine tumors including SCLC." (PMID 29866045, 2018). "ASCL1 encodes a member of the basic helix-loop-helix (BHLH) family of transcription factors, which acts as a master regulator of neurogenesis and has been shown to be overexpressed in neuroendocrine tumors." (PMID 40707954, 2025). "Studies have shown that increased ASCL1 expression in gastrointestinal-derived neuroendocrine neoplasms is detected mainly in high-malignancy carcinomas rather than in slower-progressing GEP-NETs, and at a lower frequency compared to lung neuroendocrine carcinomas." (PMID 38539512, 2024). "ASCL1 is also expressed in neuroendocrine tumors, especially in cases with poor prognoses." (PMID 27462425, 2015). "Additionally, ASCL1 is a key transcription factor (TF) in neuroendocrine tumors." (PMID 38726001, 2024). "Furthermore, ASCL1 regulates the expression of DDL3, a Notch ligand that is highly expressed in SCLC and other neuroendocrine tumors but is minimally expressed in normal tissues." (PMID 38539512, 2024). "Thus, our present findings suggested that the TGF-β-Smad-ASCL1 pathway is important in SCLC progression, and that it may also have an important role in other neuroendocrine tumors." (PMID 27462425, 2015).
lung adenocarcinoma (18 papers, 2012 to 2025). A carcinoma that arises from the lung and is characterized by the presence of malignant glandular epithelial cells. "ASCL1 confers osimertinib resistance to lung adenocarcinoma by initiating an EMT-related gene expression program in a permissible cellular environment." (PMID 38726001, 2024). "Achaete-scute homolog 1 (ASCL1) is a neuroendocrine transcription factor specifically expressed in 10-20% of lung adenocarcinomas (AD) with neuroendocrine (NE) differentiation (NED)." (PMID 28460442, 2017). "NCI-H441 human lung adenocarcinoma cells with forced Ascl1 expression and BEAS-2B human immortalized bronchial cells overexpressing MMP-7 were treated with the alkylating anti-cancer drug cisplatin and non-alkylating anti-cancer drugs etoposide and docetaxel." (PMID 23300791, 2012). "Likewise, it has been reported that ASCL1 expression is a sign of poor prognosis in lung adenocarcinomas with NE differentiation." (PMID 35489038, 2022). "However, in lung adenocarcinoma, ASCL1 expression seldom overlaps with ONECUT2." (PMID 31882655, 2019). "In lung adenocarcinomas patients, EGFR mediates the activation of RET with neuroendocrine differentiation characterized by ASCL1 expression, implicating that EGFR is a key regulator of RET." (PMID 36147490, 2022). "While ASCL1 was also overexpressed in a subset of lung adenocarcinoma, the expression of ONECUT2 and ASCL1 were barely correlated." (PMID 31882655, 2019). "To investigate if MMP-7 and MGMT are downstream genes of Ascl1, we overexpressed Ascl1 in human lung adenocarcinoma cells H441 which are normally negative for Ascl1 expression." (PMID 23300791, 2012). "Importantly, ASCL1 was sufficient to increase NE and CSC markers, which were enhanced with ENZ treatment, similar results were observed in lung adenocarcinoma." (PMID 35477723, 2022).
Stroke (14 papers, 2013 to 2025). Sudden impairment of blood flow to a part of the brain due to occlusion or rupture of an artery to the brain. "We then asked whether brain endothelial Ascl1-driven neurogenesis was associated with stroke recovery." (PMID 36535938, 2022). "Endothelial cells have been reported to modulate astrocytes to neural progenitor cell trans-differentiation through releasing microvesicles with pro-neural factor Ascl1 in a mouse model of stroke." (PMID 40702549, 2025). "If OGD is supposed to upregulate Ascl1 in brain endothelial cells, then we should be able to detect this response after stroke in vivo." (PMID 36535938, 2022). "At day 1 post-stroke, co-localizations of Ascl1 and the endothelial marker CD31 and the endothelial transcription factor ERG appeared within the ischemic boundaries." (PMID 36535938, 2022). "There was a significant increase in the number of Ascl1+ cell clusters on the stroke side (9.4 ± 4.8 clusters/section; mean+SD) compared to the uninjured side (3.2 ± 2.5 clusters/section; p = 0.014)." (PMID 32698472, 2020). "An early marker for the recruitment of parenchymal astrocytes to the neurogenic lineage after stroke or after deletion of Rbpj is the expression of the proneural transcription factor Ascl1 in astrocytes." (PMID 32698472, 2020). "In vivo enforcement of transcriptional factors (Ascl1, Sox2 and NeuroD1) successfully induced ectopic neuronal cells in the ipsilateral cerebral cortex and lateral striatum of the post-stroke mice brain." (PMID 31358888, 2019). "Taken together, the present study successfully achieved, for the first time, in vivo direct reprogramming by enforced transcriptional factors (Ascl1, Sox2 and NeuroD1) in the post-stroke mouse brain." (PMID 31358888, 2019). "In their study, they observed a downregulation of Notch receptors and ligands in astrocytes followed by the appearance of ASCL1 expression after a stroke." (PMID 30525033, 2018). "During the first 2 weeks after stroke, a robust increase in Ascl1-expressing OPCs was observed in ischemic boundary regions of the gray and white matter." (PMID 24194700, 2013). "At day 3 post-stroke, Ascl1 remained visible in brain endothelial cells." (PMID 36535938, 2022). "Finally, if brain endothelial cells can transfer Ascl1 to induce astrocyte trans-differentiation, can one augment this phenomenon to increase neurogenesis and modify outcomes after stroke?" (PMID 36535938, 2022). "At day 7 post-stroke, Ascl1 began to be detectable in GFAP positive astrocytes." (PMID 36535938, 2022). "All these data suggest that endothelial-specific overexpression of Ascl1 may contribute to neurogenesis and partly improve neurological recovery after stroke." (PMID 36535938, 2022). "The numbers of transient amplifying Ascl1+/Tomato+ progenitor cells, both as single cells and clustered, were significantly increased in the stroke side (56 ± 26 vs. 16 ± 7 single cells/section; p = 0.022; 64 ± 40 vs. 21 ± 19 clustered cells/section; mean ± SD; p = 0.023)." (PMID 32698472, 2020). "Frisén’s laboratory showed that stroke and reduced Notch signaling could elicit a latent neurogenic program with induced Ascl1 expression in striatal astrocytes, and this could produce new neurons." (PMID 28832532, 2017). "Third, although forced expression of Ascl1 alone or with other factors can regenerate both glutamate and GABAergic neurons, our study is focused on the ability of brain endothelial signals to trans-differentiate astrocytes into neural progenitors and improve outcomes after stroke." (PMID 36535938, 2022). "By 14 days post-stroke, the percentage of TUJ1 positive cells expressing Ascl1 and the number of TUJ1 positive cells were significantly higher after endothelial-specific Ascl1 upregulation." (PMID 36535938, 2022).
Stroke (continued). "In order to analyze the effects of brain endothelial overexpressing Ascl1 on neurogenesis after stroke, Tie2-Cre and VE-cadherin-Cre mice were injected with AAV-FLEx-GFP or AAV-FLEx-ASCL1-GFP and then subjected to permanent occlusion of their distal middle cerebral arteries." (PMID 36535938, 2022). "The same study showed that NICD negative striatal astrocytes generated DCX/Ascl1 neuroblasts from 2 to 7 weeks after stroke, suggesting that Rbpj deletion alone was sufficient to activate their neurogenic program." (PMID 34222228, 2021). "We found that the number of Ascl1+ cells was higher in the striatum, not including the subventricular zone, of the stroke side (121 ± 57cells/section; n = 5) compared to the contralateral uninjured striatum with Rbpj deletion only (37 ± 25/section; n = 5, p = 0.015)." (PMID 32698472, 2020).
breast carcinoma (10 papers, 2016 to 2025). "The frequency and types of ASCL1 mutations in primary breast cancer were examined using a dataset of 2051 samples with complete DNA sequencing data from the cBioPortal database." (PMID 39963143, 2025). "Our work also found that ASCL1 was a risk factor for BC prognosis patients, implying that it might promote breast cancer tumorigenesis." (PMID 36755810, 2023). "Furthermore, Western blotting, qRT-PCR, and CCK8 assays demonstrated that the expression of ASCL1 was positively correlated with chemotherapy resistance in breast cancer." (PMID 38726001, 2024). "Further analysis showed that ASCL1 knockdown resulted in the downregulation of the ATP-binding cassette transporter (ABCG2), a protein linked to drug resistance in BC, also known as the breast cancer resistance protein." (PMID 39963143, 2025). "Methylation of ASCL1, LHX8, and ST6GALNAC5, as found in cervical cancer, has also been detected in oral cancer (ASCL1), colorectal cancer (ASCL1 and ST6GALNAC5), and breast cancer (LHX8), suggesting a tumour suppressive role of these genes in these cancers." (PMID 30360578, 2018).
carcinoids (10 papers, 2010 to 2025). "Strikingly, all evaluated aSCLC were exclusively ASCL1-positive, suggesting a specific relationship between aSCLC and an ASCL1-expressing subset of carcinoids." (PMID 39185963, 2025). "ASCL1 is preferentially observed in pulmonary HG-NECs, less frequently in carcinoid tumors, while INSM1 is constantly expressed in all pulmonary NE tumors with even higher sensitivity in carcinoid." (PMID 34996493, 2022). "Direct ASCL1 knockdown with an ASCL1-specific, alleviating cyclin B1 and D1 and augmenting expression of p27Kip1 and p21Waf1/Cip1 was confirmable involved mechanisms to combat carcinoids." (PMID 33858433, 2021). "The findings suggested that inhibitory effect of chrysin on ASCL1 was effective for carcinoid management." (PMID 33858433, 2021). "ASCL1 is overexpressed in ileal NETs and in vitro experiments have shown that transient overexpression of Notch1 in carcinoid cell lines can reverse ASCL1 overexpression, indicating that Notch1 activation may be a potential therapeutic strategy." (PMID 38539512, 2024). "The effect of chrysin on ASCL1 in carcinoid cell was evaluated by using western blotting." (PMID 33858433, 2021). "In ileal NETs, ASCL1 is overexpressed and transient overexpression of Notch1 in carcinoid cell lines in vitro can reverse ASCL1 overexpression, suggesting that activation of Notch1 may be therapeutic." (PMID 29255447, 2017). "ASCL1 (p = 0.0016), BCL2 (p < 0.0001), CASP8 (p = 0.0030), CCNE1 (p = 0.0135), CDK1 (p = 0.0146), CDK2 (p = 0.0114), CDKN1A (p = 0.0107) and CDKN2A (p = 0.0002) showed lower expression in carcinoids compared to carcinomas." (PMID 26008974, 2015). "In the present study, ASCL1 showed very high counts compared to the other investigated mRNA targets and was expressed in the majority of all NET of the lung with increasing expression from carcinoids to carcinomas." (PMID 26008974, 2015). "Notably, while ASCL1—a key NE marker—predictably shows positive correlation with NE-specific genes in the NE50 gene set, its expression is absent in many carcinoids (with sample tumor histology indicated by color)." (PMID 40586102, 2025).
neuroendocrine carcinoma (10 papers, 2017 to 2025). A malignant neuroendocrine neoplasm composed of cells containing secretory granules that stain positive for NSE and chromogranin. "DLL3, an inhibitory NOTCH ligand, is overexpressed in many neuroendocrine cancers and is a downstream target of ASCL1." (PMID 29088717, 2017). "In cultured neuroendocrine cancer cells from gastrointestinal and pulmonary carcinoids, resveratrol treatment induced activation of Notch signaling, as indicated by Notch-2 induction and the suppression of achaete-scute complex-like 1 (ASCL-1), a downstream target of Notch." (PMID 35408894, 2022). "While ASCL1’s role in AML is emerging, its established function in neuroendocrine cancers suggests the tractability." (PMID 40707954, 2025). "ASCL1 is a transcription factor required for the proper development of pulmonary neuroendocrine cells while NEUROD1 is a neuronal/neuroendocrine protein that helps migration and survival of neuroendocrine carcinomas." (PMID 35263037, 2022).